HIF1A (hypoxia inducible factor 1 subunit alpha)
Diseases named in the same sentence as HIF1A in open-access papers (continued):
Sharing a sentence is not in itself a finding about the gene and the disease.
gastric tumor (continued). "In that study, the author suggested that HIF-1α not only regulates the VEGF expression in cancer cells, but also contributes to the formation of a complex proangiogenic microenvironment in gastric tumors, thereby affecting the vessel morphology and function." (PMID 24216696, 2013). "The expression of HIF-1α and IGF2 mRNA correlated in gastric tumor samples." (PMID 35681691, 2022). "Moreover, both HIF1α and OATP1B3 were strongly expressed in all three PDX tumor samples and their original clinical gastric tumor specimens." (PMID 27329598, 2016). "Therefore, miR-4646-5p could mitigate ubiquitination of HIF1A by inhibiting the target gene PHD3, thus lead to an enhanced HIF1A in Drosha-knockdown gastric tumor cells." (PMID 33875796, 2021).
hemangioma (24 papers, 2016 to 2025). A benign vascular lesion characterized by the formation of capillary-sized or cavernous vascular channels. "HIF-1α level is directly proportional to the activity and severity of hemangioma, and its overexpression is closely implicated in the increased vascularity, invasion, and progression of tumor." (PMID 33490272, 2021). "HIF-1α was significantly overexpressed in IH tissues and hemangioma-derived endothelial cells at both mRNA and protein levels." (PMID 40978048, 2025). "Hypoxia-induced factors important for postnatal vasculogenesis (SDF-1α, MMP-9, VEGF-A, HIF-1α) are upregulated in children with proliferating hemangiomas." (PMID 39997620, 2025). "The miR-199a-5p mimic suppresses the proliferation of hemangioma cells, which is reversed by HIF1A overexpression." (PMID 36835100, 2023). "We further revealed the mechanism of action of the combinatorial treatment: β-elemene in combination with propranolol inhibits proliferation, migration, and angiogenesis of hemangioma by synergistically down-regulating the HIF-1-α/VEGFA signaling pathway." (PMID 37456875, 2023). "Previous research has shown that the expression of HIF-1-α is increased in hemangioma; thus, over-expression of HIF-1-α promotes angiogenesis suggesting that the angiogenesis of hemangioma is driven by hypoxia." (PMID 37456875, 2023). "HIF-1α expression is significantly higher in hemangioma endothelial cells relative to normal endothelial cells." (PMID 36181115, 2022). "As a potent proangiogenic molecule, HIF-1α actively takes part in the formation of new vessels and the proliferation of endothelial cells in hemangioma." (PMID 33490272, 2021). "In summary, this study demonstrated that LncRNA-MCM3AP-AS1 promotes the progression of hemangioma by regulating miR-138-5p/HIF-1α axis and glycolysis." (PMID 34660700, 2021). "Propranolol decreased cell viability, migration, and tubulogenesis in hemangiomas through the HIF-1α-mediated inhibition of VEGF-A and downregulation of phosphoinositide 3-kinase (PI3K)/Akt and p38/MAPK pathways." (PMID 33419318, 2020). "HFU‐assisted dye laser can effectively reduce the tumor area, decrease the serum HIF‐1α level, and improve the prognosis in the treatment of hemangioma." (PMID 31568612, 2020). "The site and type of hemangioma and age distribution of patients were collected, and changes in data and area of hemangioma and serum HIF‐1α before and after treatment were analyzed." (PMID 31568612, 2020). "In vitro experiments demonstrated that propranolol reduces the expression of HIF-1α in hemangioma cells in a dose- and time-dependent manner, mainly by acting on β2-AR." (PMID 33419318, 2020). "Propranolol-treated hemangioma tissues were collected and the expression of hypoxia inducible factor-1α (HIF-1α) was examined." (PMID 28977119, 2017). "Propranolol suppressed the cells proliferation, migration and tube formation of hemangioma cells through HIF-1α dependent mechanisms." (PMID 28977119, 2017). "Significantly increased levels of HIF-1α mRNA and protein were found in hemangioma tissues compared with normal vascular tissues." (PMID 28977119, 2017). "Next, 50 μM propranolol used to treat the hemangioma cells for 24, 48, and 72 h showed that the propranolol gradually decreased the expression of HIF-1α level in a time-dependent manner." (PMID 28977119, 2017). "To further validate the role of HIF-1α in the propranolol-treated cells, we established HIF-1α overexpressed and knockdown hemangioma cells." (PMID 28977119, 2017). "Significantly increased HIF-1α level was found in the hemangioma tissues compared to that in normal vascular tissues, whereas propranolol treatment decreased the HIF-1α level in hemangioma tissues in a time- and dose-dependent manner." (PMID 28977119, 2017). "In the present study, we demonstrated that significantly increased HIF-1α levels were found in hemangioma tissues compared to normal vascular tissues, and its levels were decreased by propranolol treatment." (PMID 28977119, 2017).
hemangioma (continued). "We also established HIF-1α overexpression and knockdown hemangioma cells, and determined the effects of HIF-1α on the hemangioma cells proliferation, apoptosis, migration and tube formation." (PMID 28977119, 2017). "Propranolol acts as an inhibitor of angiogenesis and it was recently described to suppress proliferation, migration and tube formation of hemangioma cells through the HIF-1α-VEGF-A axis and to decrease the expression of angiogenic growth factors, as VEGF and FGF." (PMID 34041026, 2021). "In this study, we used bioinformatics method, combined with qPCR, WB, flow cytometry and other research methods to study the regulation of LncRNA MCM3AP-AS1 and miRNA/HIF-1α signaling pathway in the occurrence and development of hemangioma to explore the molecular mechanism of hemangioma." (PMID 34660700, 2021). "Propranolol treatment inhibited cell proliferation, migration, tube formation and promoted apoptosis in the hemangioma cells, suggesting that HIF-1α could serve as a therapeutic target in the treatment of IH." (PMID 28977119, 2017). "This intrinsic difference in HIF-1α expression between hemangiomas and normal tissues could result in predominance of the canonical HIF-1α pathway in VEGF signaling." (PMID 28977119, 2017). "In conclusion, significantly increased HIF-1α levels were found in the hemangioma tissues." (PMID 28977119, 2017). "However, HIF-1α mRNA and protein levels remarkably decreased in the propranolol-treated hemangiomas." (PMID 28977119, 2017). "Moreover, propranolol treatment significantly decreased cell proliferation, migration and tube formation as well as promoted cell apoptosis in HIF-1α overexpression and knockdown hemangioma cells." (PMID 28977119, 2017). "Moreover, propranolol treatment significantly decreased hemangioma cell proliferation, migration and tube formation in HIF-1α-overexpressed and knockdown cells." (PMID 28977119, 2017). "Differently, HIF-1α knockdown remarkably inhibited hemangioma cells proliferation." (PMID 28977119, 2017). "HIF-1α could serve as a novel target in the treatment of hemangiomas." (PMID 28977119, 2017). "Proliferating hemangioma (HDEC) cells downregulate miR-199a-5p (miR-199a) and upregulate HIF1A, a target of miR-199a-5p." (PMID 36835100, 2023). "Results of this study revealed that the level of serum HIF‐1α sharply declined after treatment of hemangioma with HFU‐assisted dye laser, confirming the treatment effect of ultrasonic laser therapy on hemangioma." (PMID 31568612, 2020). "On the other hand, the cell apoptotic percentage accounted for 9.1% (3.9+5.2%) in HIF-1α overexpression group and 16.7% (8.2+8.5%) in HIF-1α knockdown group, suggesting that HIF-1α overexpression abrogated propranolol-induced hemangioma cells apoptosis." (PMID 28977119, 2017). "Previous studies have confirmed elevated expression of HIF1A, IGF1, and IGF2 in hemangioma tissues." (PMID 40978048, 2025). "Moreover, several reports have implied that hypoxia-inducible factor-1α (HIF-1α) and vascular endothelial growth factor (VEGF), highly expressing in hemangioma, are major two contributors to vascular endothelial cell proliferation and abnormal angiogenesis." (PMID 33490272, 2021). "HIF-1α could inhibit VEGFA expression, whereas VEGF-mediated upregulation of IL-6 triggers the progression of hemangioma cells." (PMID 31949494, 2020). "The results showed that cell proliferation was significantly inhibited by propranolol treatment of hemangiomas and significantly increased by HIF-1α overexpression, whereas propranolol treatment completely abolished HIF-1α overexpression-induced hemangioma cells proliferation." (PMID 28977119, 2017). "On the basis of these two converging lines of evidence suggesting a role for HIF-1α in FGF23 production and in hemangioma tumor progression, we explored the hypothesis that aberrant FGF23 production in TIO tumors might also occur though a HIF-1α-dependent mechanism." (PMID 27468359, 2016).
hemangioma (continued). "A reliance on HIF-1α signaling and dependence on VEGF for survival could explain the specific response of hemangiomas rather than other tissues treated with propranolol." (PMID 28977119, 2017).
ischemic heart disease (24 papers, 2011 to 2025). "HIF1A rs2057482 polymorphism is related to the occurrence of coronary heart disease and some metabolic parameters and cardiovascular risk factors." (PMID 35733129, 2022). "Renalase expression is upregulated by a hypoxic-inducible factor (HIF-1a) mechanism under hypoxic conditions, which has been implicated in both ischemic heart disease and renal ischemia." (PMID 35322081, 2022). "In ischemic heart disease, acute HIF1α activation can be beneficial as a response to acute cardiac stress." (PMID 40034852, 2025). "In ischemic heart disease, hypoxic cardiomyocytes stimulate cardiac angiogenesis by activating the HIF-1α/VEGF signaling pathway." (PMID 41295364, 2025). "It is notable, that hypoxia-inducible factor 1-alpha (HIF-1α) is activated in ischemic heart diseases and increases mitochondrial fission." (PMID 35562962, 2022). "For example, our RNA-seq analyses demonstrated that inhibition of HIF-1α in DF-treated ECs rescued the expression of anti-inflammatory molecules KLF2, KLF4, and PPAP2B (a coronary arterial disease candidate gene identified by genome-wide association studies)." (PMID 28556776, 2017). "However, in ischemic heart disease and pressure-overload heart failure, HIF-1α activation plays a critical protective role by activating homeostatic mechanisms." (PMID 37885997, 2023). "Understanding the intricacies of HIF-1α’s role in neutrophil function may provide valuable insights for the development of novel therapeutic approaches targeting HIF-1α to mitigate inflammation and tissue damage in ischemic heart diseases." (PMID 37233182, 2023). "Nonetheless, the recent focus on activating the hypoxia-inducible factor (HIF) pathway, either by inhibiting HIF-1α degradation or by overexpressing HIF-1α, in the heart may show promise as a possible therapeutic avenue for treating ischemic heart disease." (PMID 25633836, 2015). "There were 12 angiogenesis-related targets of salidroside in coronary heart disease, among which FGF1 (r = 0.237, P = 2.597E-3), KDR (r = 0.172, P = 3.007E-2) and HIF1A (r = -0.211, P = 7.437E-3) were correlated with the coronary flow index (CFI), and salidroside docked well with them." (PMID 37308900, 2023).
ulcerative colitis (24 papers, 2015 to 2026). An inflammatory bowel disease involving the mucosal surface of the large intestine and rectum. "To explore the potential association between HIF-1α and ferroptosis in ulcerative colitis, we first subjected NCM460 cells to LPS stimulation to establish inflammatory colonic epithelial models." (PMID 40691131, 2025). "When combined with baicalein and triptolide, palmatine synergistically modulates macrophage metabolism via the HIF-1α pathway, promoting M2 polarization for ulcerative colitis treatment." (PMID 40786032, 2025). "Elevated expression levels of HIF-1α were evidenced in patients with Crohn’s disease and ulcerative colitis, indicating its protective role in mitigating inflammatory bowel disorders by improving the epithelial barrier functionality." (PMID 37965556, 2023). "Analyzing the group of UC patients according to the extent of ulcerative colitis, we found that the HIF-1α value was higher in all the test groups (E1, E2, and S) than in the C group with a statistically significant difference." (PMID 38137357, 2023). "In 2021, Lu and colleagues revealed a novel mechanism of cyclosporine A in alleviating acute severe ulcerative colitis (ASUC) by promoting neutrophil HIF-1α expression and restricting excessive neutrophil activation in the SIRT6-HIF-1α-glycolysis axis." (PMID 37199341, 2023). "Meanwhile, increased expressions of HIF1A were previously identified in the colon of DSS-induced ulcerative colitis mice, which reiterates the significance of our findings." (PMID 35764613, 2022). "Recently, a well-designed clinical trial supported the full therapeutic potential of a HIF-1α stabilizer (GB004) for the treatment of active ulcerative colitis." (PMID 35711312, 2022). "HIF is therefore essential in IBD progression and indeed Hif-1a and Hif-2a overexpression is observed in surgical specimens from ulcerative colitis and Crohn's disease." (PMID 29967068, 2018). "miR-31, a reported target of hif1a, was increased in specimens obtained from patients with active ulcerative colitis and during progression and neoplastic transformation of IBD, but it was down-regulated in NEC tissues (0.12 fold)." (PMID 26274503, 2015). "Moreover, another study demonstrated that repression of the Ras-PI3K-Akt-HIF1A axis by treatment with the Huangqin Decoction could alleviate ulcerative colitis induced by DSS in mouse models, which is in accordance with our findings." (PMID 35764613, 2022). "For instance, stabilization of HIF1A by NIX, which was highly-expressed in the intestinal epithelium of ulcerative colitis patients, was previously uncovered to facilitate the aggravation of mitochondrial damage in intestinal inflammation." (PMID 35764613, 2022). "In this regard, the bacteriostatic effects induced on Gram+ and Gram- strains, together with the inhibition of COX-2, TNFα, HIF1α, and VEGFA suggest the potential of P. mahaleb water extract in contrasting the clinical symptoms related to ulcerative colitis." (PMID 34361576, 2021). "The bacteriostatic effects induced on Gram+ and Gram- strains, together with the inhibition of COX-2, TNFα, HIF1α, and VEGFA in the colon, suggest the potential of P. mahaleb water extract in contrasting the clinical symptoms related to ulcerative colitis." (PMID 34361576, 2021). "In fact, both HIF-1α and HIF-2α are found at high levels in intestinal epithelial cells (IEC) from patients with active ulcerative colitis or Crohn’s disease." (PMID 33519819, 2020). "Preclinical studies have shown that stabilization of HIF-1α leads to improved intestinal barrier functions, and gut-targeted HIF-1α stabilizers like GB004 may be a promising therapeutic approach for ulcerative colitis patients." (PMID 36793710, 2023). "Therefore, for ulcerative colitis with the existence of IL-1βand TNF-α, the production pathway of HIF-1α is more abundant, and the activation of HIF-1α can induce the production of IL-6, IL-8 and other inflammatory mediators such as iNOS and COX-2." (PMID 32600331, 2020).
invasive breast carcinoma (23 papers, 2007 to 2023). A carcinoma that infiltrates the breast parenchyma. "Although BRCA1 and BRCA2 germline mutation-related invasive breast cancers are different in many ways, the hypoxia-related proteins HIF-1α, CAIX and Glut-1 are expressed in both DCIS and invasive lesions of BRCA1 and BRCA2 mutation carriers." (PMID 23409121, 2013). "Clinical evidence showed that HIF-1α is associated with a worse prognosis in patients with invasive breast carcinoma." (PMID 21980400, 2011). "Moreover, HIF-1α is over-expressed in about 24–56% of invasive breast cancers or even more and has been associated with increased VEGF expression, increased angiogenesis, higher tumor grade, as well as treatment failure and poor prognosis." (PMID 26760782, 2016). "As is the case with most solid tumors, 25% to 40% of invasive breast carcinomas are hallmarked by hypoxic areas driving extracellular ATP release with an overexpression of hypoxia-inducible factor-1 alpha (HIF-1α)." (PMID 37753093, 2023). "In this study, we demonstrated that HIF‐1α and Kindlin‐2 are highly expressed in invasive breast cancer and that both are correlated with its stiffness." (PMID 32436609, 2020). "Taken together, HIF‐1α and Kindlin‐2 are highly expressed and correlate with invasive breast cancer stiffness." (PMID 32436609, 2020). "In this study, we verified that the expression of HIF‐1α in invasive breast cancer is higher than in fibroadenoma, which is consistent with previous studies." (PMID 32436609, 2020). "In a large series of invasive breast carcinomas, previously classified for molecular subtypes, immunohistochemistry staining was performed for P-cadherin, HIF-1α, GLUT1, CAIX, MCT1, MCT4, and CD147." (PMID 25269858, 2014). "In conclusion, we demonstrated that aberrant P-cadherin expression is associated with the hypoxic/glycolytic and acid-resistant phenotype in invasive breast carcinomas, represented by a panel of markers including HIF-1α, GLUT1, CAIX, MCT1 and CD147." (PMID 25269858, 2014). "By using HIF-1α as a marker for hypoxia, approximately 25-40% of all invasive breast cancer samples are hypoxic; the frequency of HIF-1α-positive cells increases in parallel with increasing pathologic stage and is associated with a poor prognosis." (PMID 20492653, 2010). "Hypoxia-inducible factor (HIF)-1α levels in invasive breast carcinoma have been shown to be an adverse prognostic indicator." (PMID 18096060, 2007). "Furthermore, HIF‐1α, Kindlin‐2, and Emax were intercorrelated with each other in invasive breast cancer." (PMID 32436609, 2020). "Therefore, we set out to correlate expression of DDX3 and HIF-1α in a large set of human invasive breast cancers." (PMID 23696831, 2013). "Previous studies have shown that over-expression of CA IX and HIF-1a, surrogates for hypoxia, correlates with a poor prognosis in invasive breast carcinomas, and may enhance metastatic properties of cancer cells by modulating tumor-associated cell migration and invasion." (PMID 29206859, 2017). "We therefore studied HIF-1α overexpression in ductal carcinoma in situ (DCIS), an established precursor of invasive breast cancer." (PMID 23409121, 2013). "In conclusion, this is the first study to assess angiogenesis, proliferating ECs, HIF-1α, VEGF and TF in each stage of the hyperplasia, in situ and invasive breast carcinoma sequence in a cohort of patients." (PMID 19623180, 2009). "To test the hypoxic response in invasive breast carcinomas in relation to BNIP3, we also examined the expression of HIF-1α and its target genes Glut-1 and CAIX." (PMID 19505343, 2009). "Furthermore, one third of invasive breast cancers exhibit hypoxic TME, which could promote the HIF-1α-A2A-adenosinergic pathway, and consequently the establishment of immunosuppression." (PMID 37753093, 2023).
invasive breast carcinoma (continued). "This study therefore quantifies angiogenesis and the number of proliferating ECs in addition to the expression of HIF-1α, VEGF and TF in hyperplastic lesions, in situ and invasive breast carcinomas, to determine whether angiogenesis may have a role in dysplastic transformation." (PMID 19623180, 2009).